CERS6 (ceramide synthase 6)
Description:
Ceramide synthase that catalyzes the transfer of the fatty acyl chain from acyl-CoA to a sphingoid base, with high selectivity toward palmitoyl-CoA (hexadecanoyl-CoA; C16:0-CoA). Can use different sphingoid bases as substrates for ceramide synthesis, such as sphinganine in de novo synthesis, and sphing-4E-enine (sphingosine), (4R)-hydroxysphinganine (phytosphingosine) or sphinga-4E,14Z-dienine in salvage pathways. Other fatty acyl-CoAs such as long-chain saturated stearoyl-CoA (octadecanoyl-CoA; C18:0-CoA), myristoyl-CoA (tetradecanoyl-CoA; C14:0-CoA), and monounsaturated oleoyl-CoA (9Z-octadecenoyl-CoA; C18:1-CoA) can also act as acyl donors, but with less efficiency than hexadecanoyl-CoA. Ceramides generated by CERS6 play a role in inflammatory response (By similarity). Acts as a regulator of metabolism and hepatic lipid accumulation (By similarity). Under high fat diet, palmitoyl- (C16:0-) ceramides generated by CERS6 specifically bind the mitochondrial fission factor MFF, thereby promoting mitochondrial fragmentation and contributing to the development of obesity (By similarity).
Synonyms: LASS6
Tractability: Small molecule: a structure with a bound ligand is known. Antibody: UniProt predicts a signal peptide or a membrane-spanning region. PROTAC: ubiquitination databases record sites on it; its protein half-life has been measured.
Target class: Enzyme; Transferase
Gene: Protein-coding gene on chromosome 2 (168,456,249 to 168,775,134, forward strand). Ensembl gene ENSG00000172292.
Subcellular location: Endoplasmic reticulum membrane
Pathways (Reactome):
Metabolism: Sphingolipid de novo biosynthesis
Gene Ontology:
Molecular function: protein binding; sphingosine N-acyltransferase activity; DNA binding
Biological process: ceramide biosynthetic process; sphingolipid biosynthetic process; sphingolipid metabolic process
Cellular component: membrane; endoplasmic reticulum membrane; endoplasmic reticulum
Genetic constraint (gnomAD): Loss-of-function variants: 18 observed, 45.04 expected, observed/expected ratio (o/e) 0.4, 90% interval 0.28 to 0.59. The upper end of that interval is the gene's LOEUF score, 0.59, which puts it in group 2 of 6, group 1 being the genes least tolerant of losing a copy. Missense variants: 351 observed, 415.84 expected, observed/expected ratio (o/e) 0.84, 90% interval 0.77 to 0.92. Synonymous variants: 134 observed, 154.54 expected, observed/expected ratio (o/e) 0.87, 90% interval 0.75 to 1.
Homologues: Orthologues: chimpanzee CERS6 (100% identical), macaque CERS6 (99% identical), rabbit CERS6 (97% identical), pig CERS6 (97% identical), guinea pig CERS6 (96% identical), dog CERS6 (96% identical), mouse Cers6 (95% identical), rat Cers6 (95% identical), tropical clawed frog cers6 (79% identical), zebrafish cers6 (79% identical), Drosophila melanogaster schlank (41% identical), Caenorhabditis elegans hyl-1 (28% identical), and 1 more. Paralogues in human: CERS5 (64% identical), CERS2 (41% identical), CERS4 (41% identical), CERS3 (39% identical), CERS1 (26% identical).
Diseases named in the same sentence as CERS6 in open-access papers:
CERS6 is named in the same sentence as 70 diseases in open-access papers, as found by Europe PMC text mining. Sharing a sentence is not in itself a finding about the gene and the disease. The quoted sentences say what the papers report.
Obesity (42 papers, 2016 to 2025). Accumulation of substantial excess body fat. "Ceramide with a 16-carbon acyl chain (C16 ceramide) has been implicated in obesity, insulin resistance and liver disease and the C16 ceramide-synthesizing CerS6 is regarded as an attractive drug target for obesity-associated disease." (PMID 39528795, 2025). "CerS6-deficient mice are known to be protected from obesity induced by a high-fat diet and exhibit altered hepatic lipid utilization." (PMID 41262214, 2025). "Of these enzymes, recent observations from human and mouse studies highlighted CerS6 as a target for treating obesity-associated metabolic disease, including type 2 diabetes and NASH2,5,11–13." (PMID 39528795, 2025). "This correlation is strengthened by the findings indicating that mice deficient in Cers6 not only exhibit reduced C16:0 ceramide levels but are also protected from HFD‐induced obesity and glucose intolerance." (PMID 38192209, 2024). "Accordingly, deficiency in CerS6 in mice reduced ceramide concentration and prevented high-fat-diet-mediated obesity and glucose intolerance." (PMID 36671552, 2023). "Collectively, these observations indicate that C16:0 ceramides, as generated by CerS6 in hepatocytes, elicit diverse effects on liver metabolism in the obesity-associated deterioration of liver-specific and systemic metabolic homeostasis." (PMID 35789435, 2022). "Further, while the hepatic abundance of C16:0 ceramide is reduced in CerS6 as well as CerS5 knockout mice, only CerS6 deficient mice are protected from HFD-fed obesity, hepatic steatosis, glucose intolerance, and insulin resistance." (PMID 32455838, 2020). "Mice deficient in CerS6 were protected from HFD-induced obesity, showed improvements in glucose tolerance and insulin sensitivity, and increased energy expenditure coupled with higher fat oxidation in brown adipose tissue and liver." (PMID 32455838, 2020). "Cer d18:1/16:0 produced by ceramide synthase 6 is a key metabolite in obesity associated insulin resistance." (PMID 31521175, 2019). "Consistently, ceramide synthase 6-deficient mice were protected against obesity, IR and adipose tissue inflammation." (PMID 30242179, 2018). "Overexpression of CerS6, for example, correlates with insulin resistance, and CerS6-deficient (CerS6D/D) mice exhibit reduced C16:0 ceramides and are protected from high-fat-diet-induced obesity and glucose intolerance." (PMID 28271029, 2017). "Lack of CerS5/6 expression impacts metabolism in a diet-induced obesity model and deficiency of CerS6 can also result in behavioral defects." (PMID 29138469, 2017). "Hence, C16:0-ceramide synthesizing enzymes, CerS5 and CerS6, have been implicated in the development of obesity." (PMID 36771408, 2023). "Using the CerS6 deficient mouse model the authors demonstrated that CerS6-derived C16 Cer, in contrast to CerS5-derived Cer, could promote mitochondrial fission and insulin resistance in obesity." (PMID 32759843, 2020). "Previous publications implicated CerS5 and CerS6 in obesity and glucose intolerance." (PMID 31692231, 2020). "For example, transfer of CerS6-deficient T cells also led to reduced development of graft-vs-host disease and diminished macrophage infiltration and pro-inflammatory gene expression in the diet-induced obesity model." (PMID 29138469, 2017). "Liver-specific knockdown of CERS6 reduced C16:0 ceramide levels and protected mice from high-fat diet-induced obesity and glucose intolerance." (PMID 40143173, 2025). "In mice, a ceramide synthase (CerS6) is required for obesity-induced mitochondrial fragmentation and remodeling, and loss of this enzyme protects mice from diet-induced obesity." (PMID 40060508, 2025). "CerS6 is mainly responsible for C16:0-Cer and C14-Cer synthesis, and its expression is upregulated in obesity." (PMID 40057751, 2025).
Obesity (continued). "Increased glucose tolerance conferred protection against obesity induced by a high-fat diet, and lower hepatic ceramide levels, especially of the C16:0 species, were the outcomes of liver-specific knockout of ceramide synthase 6 (CerS6) deletion." (PMID 39807459, 2024). "Accordingly, CerS6-derived ceramides have been shown recently to interact with the mitochondrial fission factor to boost mitochondrial fragmentation in obesity and to induce mitochondrial dysfunction and apoptosis in beta-cells." (PMID 38950680, 2024). "CERS6 and MYCT1 have been studied to be associated with obesity, weight gain, and subcutaneous fats in several mammalian species, including humans, mice, sheep, and pigs." (PMID 37229195, 2023). "Upregulation of CERS6 and subsequent increase in specific acyl-chain ceramides contributes to both murine and human obesity." (PMID 37229195, 2023). "Similar to obesity, metabolic pathways involving CerS6 are dysregulated and CerS6-derived C16:0-ceramides are elevated in NAFLD patients and mice." (PMID 36771408, 2023). "The present study reveals that the adverse metabolic consequences of hypothalamic ceramide accumulation in obesity depend on endogenous ceramide production, specifically by CerS6, in distinct neuronal cell types of the hypothalamus." (PMID 38016943, 2023). "Accordingly, a critical role of CerS6-dependent C16:0 ceramide production emerged in the regulation of adipose tissue function in obesity conditions." (PMID 36671552, 2023). "We report here that the levels of several ceramide species, among them C16:0 ceramides, increase in the hypothalamus of mouse models of obesity and diabetes, likely attributable to increased CerS6-dependent ceramide synthesis in neurons." (PMID 38016943, 2023). "Targeting CerS6-dependent ceramide synthesis in the hypothalamus holds promise for obesity and diabetes therapies, offering potential advantages over complete inhibition of sphingolipid/ceramide synthesis with reduced side effects." (PMID 38016943, 2023). "In addition to our observation that CerS6-derived C16:0 ceramides promote metabolic deterioration in obesity, we have previously identified a role of skeletal muscle CerS1 and its product C18:0 ceramide in the development of obesity-associated insulin resistance." (PMID 38016943, 2023). "Ceramide accumulation, particularly in mitochondria and MAMs, contributes to the development of obesity and insulin resistance in mice, which is prevented by the ablation of the C16:0 ceramide producing enzyme ceramide synthase 6 (CerS6)." (PMID 34785538, 2022). "The link between CerS6, C16:0-Cer and mitochondrial function in the context of insulin resistance and obesity was observed in the mice model of liver-specific CerS6 ablation (CerS6Δ/Δ)." (PMID 33815291, 2021). "Liver-specific CerS6 null mice displayed a partial protection from diet induced obesity but a robust protection from glucose intolerance and insulin resistance explained by enhanced insulin signaling relative to wild type animals." (PMID 32849276, 2020). "They subsequently created CerS6 null mice, which allowed for a precise determination of the role of the enzyme in the development of obesity and fatty liver disease." (PMID 32849276, 2020). "Deletion of CerS6 from the brown adipose depots reduced diet induced obesity and improved mitochondrial beta oxidation, leading to elevations in energy expenditure." (PMID 32849276, 2020). "It has been found that the CerS6 knockout mice were protected from the development of obesity when fed a high-fat diet." (PMID 31842461, 2019). "CerS6 inhibition significantly improves insulin resistance related to obesity." (PMID 41154683, 2025). "In addition, in individuals with obesity, overexpression of ceramide synthase 6 mRNA in adipose tissue has been correlated with insulin resistance." (PMID 39458565, 2024).
Obesity (continued). "Moreover, liver CerS6 deletion or overexpression in mice suggests that C16:0 ceramide is a critical mediator of obesity and insulin resistance." (PMID 38081412, 2024). "Our findings indicate that CerS6-dependent ceramide synthesis promotes ER stress and alters mitochondrial integrity in hypothalamic neurons in response to prolonged exposure to fatty acids, contributing to systemic metabolic damage in obesity." (PMID 38016943, 2023). "Our experiments reveal functions of CerS6-derived ceramides in hypothalamic lipotoxicity, altered mitochondrial dynamics, and ER/mitochondrial stress in the deregulation of food intake and glucose metabolism in obesity." (PMID 38016943, 2023). "CERS6 expression positively correlates with BMI, body fat content, and obesity in humans." (PMID 37229195, 2023). "Thus, we aimed to investigate the specific role of hypothalamic CerS6-dependent ceramide synthesis during obesity progression in vivo." (PMID 38016943, 2023). "Mitochondrial CerS6 expression was increased in response to diet-induced obesity." (PMID 36771408, 2023). "In sum, deficiency for CerS6 in POMC neurons attenuates the diet-dependent effects on mitochondrial morphology in male mice, increases POMC neuron leptin sensitivity, and improves the insulin-dependent regulation of glucose metabolism in obesity." (PMID 38016943, 2023). "Accumulation of C16 ceramide occurs during the development of insulin resistance and CerS6 silencing may be a potential target for the treatment of insulin resistance, obesity, and type 2 diabetes." (PMID 36548725, 2022). "As discussed in more detail below, CerS6-dependent C16:0 ceramide production is increased in specific tissues during obesity development, and transgenic expression of CerS6 in primary hepatocytes is sufficient to inhibit insulin-stimulated phosphorylation of AKT." (PMID 35789435, 2022). "This is evident as targeting CerS6 to reduce C16:0 ceramides, resulted in the prevention of diet-induced obesity and glucose intolerance, whilst the ablation of CerS2 reduced C22:0 and C24:0 ceramides, increased C16:0 ceramides and contributed to spontaneous hepatocellular carcinoma development." (PMID 34385976, 2021). "Recent studies have revealed that CerS6 may play an important role in the development of obesity and insulin resistance in the liver." (PMID 33815291, 2021). "In addition, analysis of conditional CerS6Δ/Δ mice revealed the involvement of CerS6 in the development of obesity in mice." (PMID 31692231, 2020). "This is because only those C16:0 sphingolipids that are synthesized by CerS6 interact with the mitochondrial fission-associated factor Mff, and this interaction is a mediator of the increase in mitochondrial fragmentation caused by HFD-induced obesity." (PMID 32455838, 2020). "Abrogation of CerS6 protects from obesity and insulin resistance in mice." (PMID 33603666, 2020). "In mice, knock-out of the CERS6 gene provided protection against obesity." (PMID 33584790, 2020). "The mechanism by which CerS6-deficiency protects from inflammation in the diet-induced obesity model remains to be elucidated but was not directly mediated by macrophages as lineage-specific ablation of CerS6 failed to recapitulate the protective effect." (PMID 29138469, 2017). "Hence, these data indicate that CerS1-derived C18:0 ceramides in neurons of the hypothalamus do not promote the obesity-associated deterioration of glucose homeostasis, as opposed to their critical role in skeletal muscle and that of hypothalamic CerS6." (PMID 38016943, 2023). "Our observation that inhibiting CerS6-dependent ceramide synthesis in SF-1 and POMC neurons improves glucose homeostasis during HFD feeding, particularly in male mice, underscores the critical role of CerS6-derived ceramides in obesity-associated ER stress in these types of neurons." (PMID 38016943, 2023).
Obesity (continued). "Therefore, inhibition of CerS6, and perhaps CerS1 and CerS5, may serve as an attractive therapeutic approach for treating insulin resistance, obesity, fatty liver, and NASH." (PMID 32849276, 2020). "However, the CerS6 null mice were protected from HFD-induced obesity." (PMID 32849276, 2020). "Therefore, reducing CerS6 could inhibit obesity induced CerS6 overexpression, leading to improved insulin sensitivity and reductions in metabolic disorders." (PMID 31067249, 2019). "These genes (CERS6 and MYCT1) are mostly related to muscles, subcutaneous fat, and obesity in humans, mice, sheep, and pig’s meat, placing them in the list of possible candidate genes for carcass-related traits in beef cattle." (PMID 37229195, 2023). "CerS6 is another CerS isoform known to generate ceramide with C16 acyl chain, and HFD-fed CerS6 KO were protected from HFD-induced obesity and glucose intolerance." (PMID 32849282, 2020). "The crosstalk linking obesity, ceramide, and FAO might be that obesity primarily increases SFAs and CerS6, resulting in the accumulation of C16:0, which subsequently lead to dysfunction of the electron transport chain and the production of ROS." (PMID 38456906, 2024). "In contrast to what we observed in mice with CerS6 deficiency in Nkx2.1-expressing cells, inhibiting CerS1 in neurons of the hypothalamus did not affect HFD-induced obesity, systemic insulin sensitivity, or glucose tolerance." (PMID 38016943, 2023). "Intriguingly, CerS6 and its derived C16:0 ceramides localize to and accumulate in hepatic mitochondria and MAM in obesity, promoting mitochondrial fragmentation in the liver of mice, diminished mitochondrial respiratory capacity, and defective glucose handling." (PMID 35789435, 2022). "In contrast, the myocyte-specific deletion of CerS5 and CerS6 did not affect insulin sensitivity and glucose metabolism in obesity, highlighting the tissue-specific regulation and roles of distinct CerSs and their specific ceramide products." (PMID 35789435, 2022). "Hammerschmidt and coworkers showed that CerS6‐derived C16 ceramide but not CerS5‐derived C16 ceramide protects from high‐fat diet‐induced obesity and insulin resistance." (PMID 31692231, 2020). "Furthermore, we have reported previously that body-wide ablation of CerS6- but not CerS5-dependent ceramide synthesis protects mice from diet-induced obesity and insulin resistance." (PMID 38016943, 2023). "In particular, hepatic Cer 16:0, specifically formed by CerS6, but not by CerS5, binds to mitochondrial fission factor (MFF), which, activated, promotes mitochondrial fission, causing mitochondrial dysfunction, an event that has been related to insulin resistance and obesity." (PMID 37108620, 2023).